AFP (alpha fetoprotein)
Diseases named in the same sentence as AFP in open-access papers (continued):
Sharing a sentence is not in itself a finding about the gene and the disease.
tumor (continued). "The downregulation of TRIM55 expression correlated with larger tumor size and elevated serum alpha-fetoprotein (AFP), and predicted unfavorable overall and tumor-free survival." (PMID 39420007, 2024). "Other studies have discussed the possible utility of tumor markers to aid in the differentiation of HCC and cHCC-ICC if both CA 19-9 and AFP are in concordance with imaging findings." (PMID 39594833, 2024). "Marimastat treatment significantly reduced proinflammatory cytokines (Il‐1β and Il‐6), ER stress markers (CHOP and Grp78), and tumor markers (CD31 and AFP)." (PMID 38558505, 2024). "We injected nude mice bearing AFP-expressing HCC xenografts, which show iRGD-induced tumour uptake, with iRGD, a RGD control peptide or PBS, and analysed blood samples drawn 5 min before and 90 min after the injections for AFP concentrations." (PMID 38889481, 2024). "Prognostic factors included ALBI and AFP in BCLC stage B, which had a greater influence from tumor burden, in addition to the background liver function." (PMID 38452155, 2024). "Extensive research has demonstrated that the tumor microenvironment (TME) plays a crucial role in the malignant transformation of HCC, and AFP is a key factor in the TME, promoting HCC development." (PMID 38660138, 2024). "Except for tumor size, satellite lesion, and MVI, elevated AFP and capsule invasion were related to long-term survival." (PMID 38622578, 2024). "This study’s scope is limited to a specific set of miRNAs and traditional tumor markers (CA19.9, CEA, AFP)." (PMID 39458127, 2024). "Another group developed improved TCR-T against HLA-A2 restricted AFP epitope (AFP158), leading to better tumour infiltration and persistence in the tested preclinical mouse models." (PMID 38760445, 2024). "Older (≥70 years) and young (<70 years) patients with the same tumor morphologic features (MTD, focality), AFP, and portal invasion were compared." (PMID 39128104, 2024). "Further subgroup analysis reveals that TLT treatment provides greater benefits for patients with tumor diameters greater than 7 cm, accompanied by PVTT, AFP levels greater than 400ng/ml, and being in the Child-Pugh A stage." (PMID 39411718, 2024). "Previous studies have revealed that early recurrence of HCC is associated with both clinical and tumor traits, such as male gender, high levels of bilirubin and alpha-fetoprotein (AFP), tumor size, and microvascular invasion." (PMID 38826785, 2024). "Alpha‐fetoprotein (AFP) is often elevated in patients with OYSTs, serving as a crucial tumor marker for diagnosis and monitoring response to therapy." (PMID 39687655, 2024). "Research has extensively explored AFP in HCC, linking it to tumor growth through various mechanisms." (PMID 39135041, 2024). "Alkaline phosphatase, preoperation alpha‐fetoprotein level, PNI, tumor number, and tumor size were identified as independent prognostic factors for ML model construction." (PMID 39440446, 2024). "Considering the HAP-III model, we finally selected five factors, including log AFP, ALB, Log TBLT, major tumor size and intrahepatic lesion number, to develop a deepHAP IV model." (PMID 38434985, 2024). "Tumour markers carcinoembryonic antigen (CEA), alpha-fetoprotein (AFP), cancer antigen 19-9 (CA19-9), and prostate-specific antigen (PSA) had normal values." (PMID 39337879, 2024). "As only mice with AFP expressing HCCs can show an iRGD-induced tumour-to-blood transport of AFP, we examined the levels of APF in tumours and corresponding livers of TGFα/c-myc HCC mice by immunoblotting." (PMID 38889481, 2024). "A univariate Cox hazard regression analyses identified ascites volume, apart from AFP, albumin, bilirubin, AST, tumor count, and tumor size, as significant prognostic factor." (PMID 39019953, 2024).
tumor (continued). "While established markers like alpha-fetoprotein (AFP), des-gamma-carboxy prothrombin, and AFP-L3 remain relevant, promising candidates include circulating tumor DNA, microRNAs, long noncoding RNAs, extracellular vesicle, and metabolomic biomarkers." (PMID 39451600, 2024). "Second, the variables included in the prediction model based on BSR were as follows: gender, smoke, LVI, LNM, tumor size, differentiation, invasion depth, RBC, AFP, Hb, with an AUC of 89.9 (86.8, 93.1)." (PMID 39513114, 2024). "Alpha-fetoprotein (AFP), predominantly secreted by HCC cells, is recognized as a significant tumor biomarker for diagnosing HCC." (PMID 39227992, 2024). "Laboratory tests, including liver function and tumor markers such as carbohydrate antigen 199 (CA199), carbohydrate antigen 125 (CA125), carcinoembryonic antigen (CEA), and alpha-fetoprotein (AFP), all yielded results within the normal range." (PMID 39151515, 2024). "We chose 13 variables for analysis, namely, age, sex, T stage, N stage, M stage, histological or clinical grade, tumor number, max tumor size, MVI, AFP, fibrosis, chemotherapy, and surgery." (PMID 39286027, 2024). "Subgroup analysis showed that patients with larger tumor, extrahepatic metastases, PVTT type I/II, and higher alpha-fetoprotein (AFP) level appeared to benefit more from TACE plus lenvatinib." (PMID 39474615, 2024). "In our case, due to the patient’s refusal of liver biopsy, mildly elevated AFP, high HBV load, and slight arterial phase enhancement, the tumor was suspected to be HCC." (PMID 39411128, 2024). "The immune classification ranked 8 (AUC = 0.67), while other variables with high rankings were mostly tumor features, such as TNM stage, microvascular invasion (MVI), and serum AFP level, which were consistent with previous findings." (PMID 38826785, 2024). "The serum concentration of AFP is over-expressed in conditions such as HCC, hepatoblastoma and teratoma in adults, featuring this protein as a valuable serum marker for tumor diagnosis and drug resistance and for monitoring therapeutic efficacy." (PMID 38473878, 2024). "This study aims to investigate the potential of miR-18a and miR-532 as biomarkers for CCA by exploring their correlations with clinical parameters and traditional tumor markers such as CA19.9, CEA, and AFP." (PMID 39458127, 2024). "Blood tumor markers such as human chorionic gonadotropin (hCG), lactate dehydrogenase (LDH), and alpha-fetoprotein (AFP) have been investigated, with LDH showing elevated levels in a significant proportion of cases." (PMID 39452478, 2024). "For instance, a patient with I-O and MTT (0 points) had an AFP >400 ng/ml (83 points), PIVKA-II >4 0mAU/ml (39 points), complete tumor capsule (0 points), and Edmondson-Steiner grade III-IV (60 points)." (PMID 39170098, 2024). "Univariate analysis showed that the serum AFP and PIVKA-II level, tumor size, tumor boundary, intra-tumoral artery, necrosis, KP gross morphology, and KP agent clearance pattern were significantly related to MVI-positive (all p < 0.05)." (PMID 39466459, 2024). "e. in the range of tumour-free DEN-CCl4-treated animals, whereas iRGD was less effective in mice with small HCCs and high basal blood AFP levels." (PMID 38889481, 2024). "Following LASSO regression screening, ALP, preoperation AFP, ALB, PT, PNI, tumor size, and tumor number were identified as closely related to the OS of HCC patients after ablation." (PMID 39440446, 2024). "Diagnosis primarily relies on tumor markers (human chorionic gonadotropin, HCG, and alpha-fetoprotein, AFP) in the blood and/or cerebrospinal fluid (CSF)." (PMID 38790424, 2024). "Baseline differences existed in several variables between the two groups, including sex, AFP, PIVKA-II, tumor size, tumor number, MVI, satellite lesion and tumor capsule, while the other variables showed no statistical differences." (PMID 39170098, 2024).
tumor (continued). "Five variables were included in the model: the size of the tumor, BCLC B sub-classification, AFP, ALB, and the number of lesions." (PMID 38434985, 2024). "Tumor markers, such as CEA, CA 19–9, CA 125, and AFP, are cell surface glycoproteins produced by cancer cells and indicate the malignant characteristics of tumors." (PMID 39039481, 2024). "For adjusted Cox regression models, tumor micronecrosis improved the AUC value of Milan criteria from 0.705 to 0.738, the AUC value of MELD score from 0.682 to 0.738, and the AUC value of AFP level from 0.566 to 0.664." (PMID 36698095, 2023). "Capecitabine significantly inhibited PDX tumor growth and reduced the expression of AFP and CEA proteins in the tumor tissues (all Ps<0.05)." (PMID 36742145, 2023). "The AFP mRNA expression rate exceeds 100% in the advanced stages of HCC and also would predict tumor recurrence following hepatectomy." (PMID 37509493, 2023). "In the univariate analysis, tumor size, LEN combined with TIT, and AFP levels were included as variables." (PMID 37762018, 2023). "The nomogram to predict the probability of recurrence was generated based on the following six independent prognostic factors: age, tumor number, MVI grade, preoperative AFP level, preoperative CA19-9 level, and ECOG PS." (PMID 37689775, 2023). "Our study results demonstrated that AFP, PCA, and tumor location are statistically significant predictors in the differential diagnosis of GHA from GA." (PMID 37538113, 2023). "Also, AFP can regulate tumor growth, and suppressing it may be an effective treatment." (PMID 37266135, 2023). "One of the traditional serum tumor markers for detecting and tracking HCC commonly used is alpha-fetoprotein (AFP), its role evolving over time." (PMID 36899960, 2023). "Pre-operative tumor markers revealed normal lactate dehydrogenase (LDH) at 150 U/L, elevated beta-hCG (hCG) at 2,739 mIU/mL, and elevated AFP at 13.23 ng/mL." (PMID 37485120, 2023). "Tumor-associated antigens (TAAs), such as carcinoma embryonic antigen (CEA), alpha-fetoprotein (AFP), and carbohydrate antigen 125 (CA125), are widely used in clinical tumor diagnosis." (PMID 37280679, 2023). "PIVKA-II has also been applied as a tumor marker for HCC in recent years, and it can be used as a complement to AFP to improve HCC diagnosis." (PMID 37689775, 2023). "Immunohistochemistry staining showed α-fetoprotein (AFP), carcinoembryonic antigen (CEA), and E-cadherin were strongly positively expressed in primary human and PDX tumor tissues, with a high degree of similarity." (PMID 36742145, 2023). "Regarding tumor biomarkers, the present investigation found that DENA-treated rats had significantly elevated serum AFP and CEA levels." (PMID 36850982, 2023). "Next, we developed a model using the BSR approach, with variables including sex, ablation history, and immunotherapy history, BCLC stage, tumor number, PNI, and LMR and AFP indices." (PMID 37105140, 2023). "Higher expression of GLS1 meant the higher expression of AFP, GPC3, Ki67, and VEGFR2; higher T and TNM stages; and higher Edmondson–Steiner grade, which indirectly reflected the relationship between GLS1 and tumour proliferation and invasion ability." (PMID 37946141, 2023). "Multivariate logistic regression analyses revealed that tumor location, PCA, and serum AFP level were independent predictors of differentiation between GHA and GA." (PMID 37538113, 2023). "The two reports raise attention to the universality of AFP, which reflects progressed dedifferentiation or retrodifferentiation of RCC cells as a result of the complexity of genomic instability and tumor heterogeneity." (PMID 37781207, 2023). "Preclinical studies in mice have shown that the LNP-AFP-mRNA vaccine can elicit AFP-specific CD8+ T cell responses and provide protection against AFP-expressing HCC tumor challenges." (PMID 37631925, 2023).
tumor (continued). "Remarkably, the absolute values of several tumor markers CEA, CA 15-3, CA 125 and AFP were significantly higher on the Vista LOCI platform as compared with the MP method and vice versa for CA 19-9." (PMID 37835844, 2023). "All tumor markers, including carcinoembryonic antigen (CEA), carbohydrate antigen 19-9 (CA19-9), alpha-fetoprotein (AFP) and protein induced by vitamin K absence or antagonist-II (PIVKAII), were within the normal ranges." (PMID 37121923, 2023). "The sensitivity, specificity, and AUC value of several exosomal lncRNAs are better than conventional tumor markers, such as CEA, CA19-9, and AFP." (PMID 36765913, 2023). "We generated a nomogram to predict the probability of survival at 6, 9, and 12 months based on 7 variables: BCLC stage, previous TACE and immunotherapy history, tumor number, PNI, log (AFP), and log (PLR)." (PMID 37105140, 2023). "Currently, many circulating tumor markers such as carcinoembryonic antigen, CA19-9, CA125, CA50, and alpha-fetoprotein have been tested in the clinic for GC detection; however, none of them has optimal sensitivity and specificity." (PMID 37572185, 2023). "In the low-AFP group, baseline DCP level was a predictor of OR, and the tumor burden of up-to-seven criteria was a predictor of early PD." (PMID 37296889, 2023). "Elevated serum AFP in HCC patients is correlated to poor differentiation, microvascular invasion and tumor recurrence, which is consistent with the biological behavior of HCCs with high Ki-67 LI." (PMID 37456233, 2023). "Among them is the alpha-fetoprotein (AFP), which is a single-chain glycoprotein, the element of the yolk sac responsible for tumor production." (PMID 37627177, 2023). "According to another study, immunosensors use DNA and RNA as biorecognition elements by simultaneously detecting two tumor markers, carcinoembryonic antigen (CEA) and alpha-fetoprotein (AFP)." (PMID 36679468, 2023). "Alfa faeto protein (AFP) as a tumour marker for HCC has insufficient sensitivity and specificity for tumour detection when used alone." (PMID 37432493, 2023). "In addition, logistic regression nomogram prediction model based on high AFP level, unsmooth tumor edge, enhancement around aneurysms, and imaging features of hepatobiliary phase (HBP) T1 weighted image and HBP-T1 map could be effectively used to evaluate the clinical results of MVI in HCC patients." (PMID 36973651, 2023). "The AUC values were 0.816 for AFP and 0.968 for EV-SF3B4 when compared against non-tumor (NT) conditions inclusive of HC, CH, and LC to HCC." (PMID 37899451, 2023). "Binary logistic regression analysis was used to analyze the variables [AFP, CEA, tumor location, CT attenuation values at the portal venous phase (PCA), and delayed phase (DCA)] with significant between-group differences." (PMID 37538113, 2023). "Concerning tumor markers, NSGCT patients had also significantly higher levels of AFP (strong difference), HCG (moderate difference) and LDH (weak difference)." (PMID 37669975, 2023). "But only among AFP-positive HCC patients, we found that patients in the high HLA-DR+ T cell ratio group had a lower rate of postoperative tumor progression than patients in the low HLA-DR+ T cell ratio group." (PMID 36873738, 2023). "The study suggested that ephrinA1 expression contributes to the malignant characteristics of AFP-producing HCC, influencing tumor cell growth, angiogenesis, invasion, and metastasis." (PMID 37444544, 2023). "Compared with the nonrecurrence group, the recurrence group had higher pretransplant AFP levels, more frequently underwent LRT, had higher tumor burdens, and had higher rates of microvascular invasion and viable tumors." (PMID 36900345, 2023). "The two groups were similar in the number of cases with AFP ≥400 ng/mL, Child–Pugh class A, BCLC stage, major tumor size, and tumor number at initial hepatectomy." (PMID 36722129, 2023).
tumor (continued). "Alpha-fetoprotein (AFP) level, GLR, and SII were stronger predictors of HCC recurrence than the age, maximum tumor diameter and tumor number." (PMID 37152021, 2023). "For example, GLS was differentially expressed in distinct age stages, BMI groupings as well as different tumor stages, and DLD was differentially expressed in alpha-fetoprotein levels." (PMID 36843949, 2023). "Both scores, which incorporate different predictor variables, such as AFP, NLR, tumor number and size, tumor differentiation and microvascular invasion, have shown to be superior in predicting the risk of recurrence than the Milan criteria." (PMID 37685524, 2023). "Because the low sensitivity of AFP is becoming increasingly difficult to meet the needs of early diagnosis of HCC, people begin to continually look for new tumor markers." (PMID 36964524, 2023). "In both the ‘neutral’ and ‘pituitary’ subset, AFP/HCG + patients had significantly larger tumors and elevated LDH as compared with the AFP/HCG- patients, suggestive for a generally higher tumor burden." (PMID 37669975, 2023). "The model to predict early recurrence was composed of the parameters sex, tumor size, tumor number, MVI, albumin-bilirubin (ALBI) grade, and serum AFP." (PMID 37972101, 2023). "Tumor markers: Carcinoembryonic antigen (CEA): > 100.00 ng/ml, alpha-fetoprotein (AFP): > 1000.0 ng/ml, carbohydrate antigen 125(CA125): > 600.0U/ml, carbohydrate antigen 199(CA199):554.63U/ml." (PMID 37660086, 2023). "Carbohydrate antigen 724 (CA724), alpha-fetoprotein (AFP), neuron-specific enolase (NSE), and carbohydrate antigen 211 (CA211) are instrumental in tumor progression, and their clinical value in patients with gastrointestinal cancer has been reported." (PMID 38067346, 2023). "The tumor initially appeared to have an internal cystic component, although it was a space between the BDTT and the bile duct wall, and the AFP and PIVKA-II were within the standard values." (PMID 37121923, 2023). "In summary, the findings indicate that combined anti–PD-L1 and AFP immunization increased activated CD8+ T cells, including AFP499+ CTLs, inducing the dramatic inhibition of most tumor lesions in c-MYC/Mcl1 mice." (PMID 37040183, 2023). "Overall, the results indicate that methylation markers were more effective than AFP and PIVKA-II in monitoring LRT response and predicting early tumor progression." (PMID 37760434, 2023). "Combined AFP immunization and anti-PD1 treatment significantly suppress c-MYC/Mcl1 tumor progression." (PMID 37040183, 2023). "AFP plays a crucial role both in the induction of growth and progression of HCC and is responsible for the immunosuppressive environment around this tumor." (PMID 36768863, 2023). "The PIMET score held predictive value regardless the gender, age, etiology, Eastern Cooperative Oncology Group (ECOG) performance status, tumor size, the presence of MVI, and alpha-fetoprotein (AFP) level." (PMID 36911686, 2023). "The patient was followed up after surgery every three months with gynecologic ultrasound and analysis of tumor markers (CEA, AFP, CA19-9, CA-125, HE4)." (PMID 37479970, 2023). "Multivariate Cox regression analysis showed that the main prognostic factors affecting the survival of patients were tumor number, PVTT type, alpha-fetoprotein, and treatment mode." (PMID 36920551, 2023). "As tumor markers that tend to be more highly expressed in HCC cells while lowly expressed in normal hepatic cells, GPC3 and AFP can aid in the direct targeting of tumor cells by cellular therapy modalities, such as monoclonal antibodies and Car-T." (PMID 38173713, 2023). "Collective evidence suggests a positive correlation between AFP and PIVKA-II levels and clinicopathological performance, such as tumor size, tumor differentiation, and vascular invasion." (PMID 37189543, 2023). "Alpha-fetoprotein (AFP) is a commonly used serum biomarker for assessing HCC management, tumor progression, and treatment response." (PMID 37762018, 2023).